CRP (C-reactive protein)
Diseases named in the same sentence as CRP in open-access papers (continued):
Sharing a sentence is not in itself a finding about the gene and the disease.
infection (continued). "Some authors suggest that infections in T2DM should be treated with antibiotics and indicate that medication with fluoroquinolone antibiotics may decrease elevated CRP values in diabetic rats." (PMID 35620114, 2022). "Since both CRP and procalcitonin levels elevate several hours after disease onset while the DNI increases 12 h before the initiation of organ failure in patients with severe infection, the DNI can help diagnose and initiate treatment against infections faster." (PMID 35926065, 2022). "No subjects had CRP levels over 10, the baseline for moderate inflammation, confirming the absence of acute infection or injury (data not shown)." (PMID 36557272, 2022). "We considered higher levels of CRP and involvement of multiple spaces were representative of more severe infection, but they did not necessarily mean that DNI would lead to esophageal involvement or esophageal perforation." (PMID 35624431, 2022). "Similar to CRP, the mRNA level of TNF-α in rRGNNV-B2-M1 and rRGNNV-B2-M2 infected zebrafish was also significantly lower than that in wtRGNNV and rRGNNV-infected zebrafish with higher virus titer (1.45 × 106 TCID50/mL and 1.45 × 105 TCID50/mL) infection." (PMID 36016359, 2022). "Furthermore, a progressive increase in CRP and PCT values can indicate an active state of infection, with values exceeding 100-fold higher than baseline." (PMID 36189371, 2022). "PCT and C-reactive protein are significantly correlated with the severity of bone infection, but only PCT can distinguish whether it is a complex infection." (PMID 35531297, 2022). "Additionally, acute phase reactants, such as lactate dehydrogenase (LDH), ferritin (FER), C-reactive protein (CRP) and D-dimer (DD) were found to be prominent in the MOF phase of the infection." (PMID 36614820, 2022). "Our results confirmed that the nCD64 index effectively distinguished children with and without infections, and also had better diagnostic performance than PCT and CRP." (PMID 36522701, 2022). "On the contrary, CRP and WBC accompanying infection decrease with age." (PMID 35628858, 2022). "When the indexes of WBC, CRP, and ESR returned to normal or the abnormal inflammatory indexes were controlled within the optimal cutoff value, the occurrence of postoperative infection could be reduced." (PMID 35813227, 2022). "CRP and IL-6 levels continued to increase until 14 days after admission in patients who died within 30 days, which reflects more severe infection or non-infectious inflammatory conditions." (PMID 36555941, 2022). "Moreover, whether an active infection and AMI coexisted cannot be completely excluded, because in the setting of AMI or AMI complicated by CS, inflammatory indicators, such as neutrophil and C-reactive protein, are usually elevated and may cause potential confounding effects." (PMID 36698952, 2022). "Therefore, the combination of CRP + NLR and SII was considered to almost accurately reflect the severity of the infection and the relative degree of inflammation." (PMID 36503406, 2022). "Among the patients with culture-negative infection, one patient had a fistula and the other cases each had an elevated CRP, elevated synovial WBC count and elevated synovial PMN%." (PMID 36402933, 2022). "The infection-related parameters C-reactive protein and procalcitonin likewise did not vary between CHIP-positive and CHIP-negative patients." (PMID 36311800, 2022). "Clinicians identified a potential value for POC CRP testing in OOH care, notably for supporting decision making when there was clinical uncertainty about whether an infection was likely to be viral or bacterial." (PMID 35892398, 2022). "Regardless of the presence of respiratory symptoms, all 13 children with a bacteremic infection had a MxA/CRP ratio below the cutoff value of 18.6, and all those without respiratory symptoms had a blood MxA level below the cutoff value of 256 μg/L." (PMID 35080443, 2022).
infection (continued). "Altogether, a relatively low number of febrile cases with confirmed infection, either a bacterial infection (7/49; 14.3%) or a non-bacterial (11/74; 14.9%) were tested negative for CRP (< 10 mg/L)." (PMID 36536340, 2022). "If WBC, CRP and ESR levels were still elevated after four weeks, intravenous antibiotics were continued until blood parameters normalized, mainly due to the fear of incomplete eradication of the infection." (PMID 36564738, 2022). "Clinical suspicion is also strengthened by the presence of elevated acute phase reactants (C-reactive protein, procalcitonin, leukocytosis) early after cardiac surgery with no evident focus of infection, especially when blood cultures are negative." (PMID 35807126, 2022). "C-reactive protein (CRP) is the main acute-phase protein with a rapid and sharp increase in plasma concentration during infection and tissue damage and may be a biomarker for pulmonary exacerbation manifestation and therapeutic response." (PMID 36015068, 2022). "Our results have shown with the clear of infectious foci, IL-6 returned to the baseline faster than CRP and suggested no recurrent infection." (PMID 36299571, 2022). "The kinetics of CRP is such that the infection group diverges from non-infection after day two, which persists to two weeks post-operatively." (PMID 35991254, 2022). "Another non-cytokine polypeptide, named C-reactive protein (CRP), is an acute inflammatory protein that increases its concentration at sites of inflammation or infection." (PMID 36077213, 2022). "A possible explanation for these results is that in the study the patients are not in the acute phase of the infection, in addition, in this same group an elevation of IL-6 was found, which would elevate hepatic synthesis of CRP." (PMID 36090983, 2022). "Among inflammation and infection markers, only C5a correlated positively with blood levels of S-spike proteins (r = 0.22; p = 0.0011) and negatively with CRP (r = − 0.17; p = 0.046) but not with other inflammatory markers." (PMID 35953544, 2022). "There was a significant difference in serum CRP levels between infection and non-infection groups (27 mg/l vs. 7.1 mg/l, p < 0.001)." (PMID 33515325, 2022). "The small improvement of the best generated models over CRP and PCT was confirmed by the reclassification of patients that showed a discordance between the infection status assigned by the adjudication committee and the decision to treat with antibiotics by the physician." (PMID 36362791, 2022). "CRP is nonspecific and can be elevated secondary to infection, trauma, inflammation, and is also influenced by age and sex." (PMID 34478414, 2022). "Serum CRP levels were compared between infected and non-infected cases, between infection subgroups, as well as between different species of infecting microorganisms." (PMID 33515325, 2022). "The non-specific inflammatory markers indicating infection, such as procalcitonin, C-reactive protein, adenosine deaminase (ADA), and lactate dehydrogenase (LDH), were significantly increased in the TM group." (PMID 36339344, 2022). "The concentrations of CRP, a suggestive or discriminatory indicator of bacterial (not viral) infection, were significantly increased by 79.7% and 54.3% (p < 0.01), respectively, in serum and colonic tissues in the LT group compared with the SA group." (PMID 36012293, 2022). "Efforts to shed light on the mechanisms revealed that one of the hallmarks of CRP function, activation of the classical complement pathway, was not involved in protecting mice from infection." (PMID 35402541, 2022). "We found that approximately 50% of the infants reported to have symptoms of diarrhea or ARI or fever based on maternal recall in the past 14 days had no infection as indicated by elevated CRP and AGP levels." (PMID 36211493, 2022). "In the case of infection or some tissue damage, CRP content usually increases rapidly, and it is a non-specific inflammatory marker." (PMID 35372482, 2022).
infection (continued). "In addition, many reports have shown that WBC count, CRP level, ESR, and PCT level play an important role in the diagnosis of early infection." (PMID 35813227, 2022). "Concurrent infection was defined as patients with clinical symptoms of fever or/and purulent sputum, elevated white blood cell (WBC) counts, C-reactive protein (CRP), erythrocyte sedimentation rate (ESR), and/or lactate dehydrogenase (LDH), or positive pathogen tests." (PMID 35784345, 2022). "Septic biomarkers such as CRP and PCT are raised in response to surgical trauma and infection." (PMID 36475186, 2022). "Indicators such as white blood cell count, CRP, PCT, IL-6, and albumin may reflect the state of the body after infection to varying degrees." (PMID 36237437, 2022). "An increasing body of evidence suggests that, in addition to functions in host defense against infections, the acute-phase proteins CRP, AAT, and SLPI are part of anti-inflammatory negative feed-back loops." (PMID 36105198, 2022). "In patients with acute HF whose decompensation was not triggered by infection, CRP was an excellent prognostic marker for both HFrEF and HFpEF with a similar effect size." (PMID 36620625, 2022). "A septic screen was done which did not reveal any focus of infection, though the C reactive protein was elevated." (PMID 36584202, 2022). "When a severe infection is caused by an inflammatory disorder caused by pathogen infection, particularly negative bacilli, serum PCT and CRP levels rise rapidly." (PMID 36189371, 2022). "At the last follow-up, no sign of infection was noted, and the knee function was good, with normal CRP and ESR." (PMID 36506031, 2022). "At the last follow-up, no sign of infection was noted, and the hip function was good, with normal CRP and ESR." (PMID 36506031, 2022). "Although CRP is a sensitive infection marker, it seems somewhat non-specific for determining local wound infection status." (PMID 35884890, 2022). "The highest CRP concentration was found post-mortem in patient #2 (CRP 100 mg/L, PMI 7 days) and was related to a mixed, purulent infection of the skin and soft tissue of the lower limb stump (etiological agents: Enterococcus and Klebsiella; both present in the blood collected post-mortem)." (PMID 35215147, 2022). "As non-specific biomarkers, the levels of CRP and IL-6 are commonly used to assess the presence and severity of acute and chronic inflammation, infection, tissue damage, and cancer." (PMID 35756643, 2022). "C-reactive Protein (CRP) is a routinely measured blood biomarker of inflammation and infection." (PMID 36387521, 2022). "Currently, white blood cell (WBC) count, erythrocyte sedimentation rate (ESR), and C-reactive protein (CRP) are cheap, easy to use, and widely available traditional blood inflammatory markers, which can provide preoperative information for diagnosing infection." (PMID 36309703, 2022). "For diarrhea reported symptoms, 42.4% of infants had no indication of infection, while for acute respiratory reported symptoms, 42.6% had no indication of infection as measured by CRP and AGP levels." (PMID 36211493, 2022). "Physicians tend to rule out infection in patients with normal CRP and PCT levels and ambiguous clinical presentations." (PMID 36555941, 2022). "C-reactive protein (CRP) is an acute phase reactant widely used in clinical practice as a marker of infection and/or inflammation owing to the fact that its synthesis rapidly and dramatically (up to 10,000-fold) increases after tissue injury or infection." (PMID 36177015, 2022). "In 11 cases this was because of missing CRP levels, most cases dated from the early 2000’s when CRP was not regularly used to monitor infection." (PMID 34046689, 2022). "C-reactive protein is a nonspecific indicator of the inflammatory response, influenced by many factors, including surgical trauma, fracture, infection, and tumor." (PMID 35067910, 2022).
infection (continued). "Based on the clinical presentations, microbial detections, and significant increase in WBC counts, neutrophil proportion, and the level of CRP and PCT in the blood test, the patient’s disease progression seemed to be a combined effect of PPMV-1 and multi-drug-resistant ABA infection." (PMID 35290154, 2022). "The current biomarkers of infection, such as leukocyte counts and C-reactive protein (CRP), are either non-specific or suffer from a delayed onset of production and slow half-life." (PMID 35861876, 2022). "In the process of infection and tissue injury, IL-6 responds more rapidly than WBC and CRP." (PMID 35794529, 2022). "C-reactive protein (CRP) is an acute-phase reactant generated by the liver and other organs in response to the release of IL-6, and it is a sensitive biomarker for a variety of inflammatory disorders like infection and tissue injury." (PMID 36267156, 2022). "For example, ESR and CRP are nonspecifically elevated by infection, and they can be normal in more than half of RA patients, regardless of disease activity." (PMID 35169224, 2022). "Since the current study excluded patients with active infection or other conditions like inflammatory diseases, the predictive value of ESR and CRP for BD activity is limited and needed to be further evaluated in these conditions (such as complicated infections)." (PMID 35144674, 2022). "C-reactive protein (CRP) is a non-specific inflammatory marker whose levels rise in response to infection, including active TB." (PMID 35550621, 2022). "CRP is considered a non-specific systemic inflammatory biomarker and is widely used to monitor infections and inflammatory conditions." (PMID 35888650, 2022). "The wtRGNNV infection increased mRNA level of CRP in zebrafish larvae as compared with that in non-infection control, whereas rRGNNV-B2-M1 and rRGNNV-B2-M2 infection caused a significant decrease in the mRNA expression of CRP as compared to wtRGNNV." (PMID 36016359, 2022). "A low CRP after 48 h is also a great help to end antibiotics early if a suspected infection was not real." (PMID 36233375, 2022). "Despite the monoculture of numerous Enterococcus faecalis from a cardiac blood sample, the post-mortem examination of a CRP concentration did not suggest any infection (CRP 0.0 mg/L) despite the autopsy results, which were conclusive." (PMID 35215147, 2022). "Daily complete blood count (CBC) and C-reactive protein (CRP) tests were performed to monitor any signs of infection and no specific findings were identified." (PMID 36086689, 2022). "CRP is widely used to indicate infection, but it is a slow prognostic marker not peaking until 48–72 h after the onset of neutropenic fever." (PMID 34255216, 2022). "None of the health facilities assessed had chlorhexidine for cord care to prevent infection, and none of the facilities had C-reactive protein tests for assessing the possibility of infection." (PMID 35248027, 2022). "In patients with infection, the CRP level decreased with the time of hospitalization, but in patients without infection, the CRP level remained high." (PMID 36555941, 2022). "Before starting the 21-day rehabilitation program, all patients showed no signs of infection, and their health status was confirmed by CRP parameter < 5 mg/L." (PMID 35401921, 2022). "There were differences in their characteristics (age, infection source, CRP, PCT, etc.), the lack of cytokine information in the control group, and the fact that patients receiving surviving MSC therapy required a longer ICU stay." (PMID 35784641, 2022). "Expert guidelines to direct this decision-making process have been available for several years with many algorithm-based guidelines incorporating the popular biomarker C-reactive protein (CRP) and/or procalcitonin (PCT) for the presumed diagnosis of an infection." (PMID 35436301, 2022).
infection (continued). "A declining trend in log CRP was seen by excluding the 2 subjects strongly suspected of having an infection, although no increase in albumin levels was demonstrated." (PMID 35949598, 2022). "Multiplexed detections of CRP, PCT, and IL-6 can cover the whole period of infection." (PMID 35144683, 2022). "Increased levels of POC CRP can be associated with serious infections, however we do not recommend physicians to solely base their clinical decision on POC CRP." (PMID 36333682, 2022). "CRP and PCT are common infection biomarkers in clinic, but they also have some limitations." (PMID 35741271, 2022). "Similarly, the commonly used biomarkers of infection, such as PCT and CRP, presented with higher levels in patients with septic shock, as compared to those without septic shock." (PMID 35967346, 2022). "In our research, CRP, WBC, and NC had extremely low cut-off values in the early hours of infection." (PMID 35582414, 2022). "Laboratory examination tends to show an increase in the level of erythrocyte sedimentation rate (ESR), white blood cell count, C-reactive protein (CRP), and other indicators of infection, coupled with the low echogenicity of nodules on ultrasound and decreased iodine absorption rate." (PMID 34996368, 2022). "However, one patient stopped receiving treatment as a result of an increase in the inflammatory marker C-reactive protein (CRP), which suggested a potential infection." (PMID 36381899, 2022). "Hence, CRP measurements have potential utility as a clinical tool in assessing disease status and progression, including CVD, some infections, and cancer." (PMID 35996695, 2022). "This framework does not translate easily to OWOB or other chronic conditions where inflammation is not the response to a single infection, and is not consistent with observations of associations between OWOB and CRP." (PMID 36475018, 2022). "C-reactive protein (CRP) is a non-specific inflammatory marker that typically begins to increase 6–8 h after infection onset." (PMID 35874568, 2022). "It was observed that postoperative wound infections had higher mean CRP values on the third and seventh postoperative days than those who did not have a postoperative infection." (PMID 35350520, 2022). "Resolution of infection was exhibited in all, as noted by normalization of the ESR and CRP levels." (PMID 35962360, 2022). "Thus, excessive secretion of angiotensin II post infection by SARS-CoV-2 increases two specific disease parameters of RA namely ESR and CRP." (PMID 34181704, 2021). "There were probably no patients with acute infection in this study, because their Alb and CRP were measured at discharge, and at that time they had no clinical symptoms and physical findings of infection." (PMID 34294776, 2021). "It has also been reported that the plasma level of CRP is not a biomarker to predict infection severity." (PMID 35154611, 2021). "In our study, a simultaneous measurement of C-reactive protein to rule out infection was not performed at the time of laboratory serum ferritin measurement, as recommended by the AAP." (PMID 34943355, 2021). "Patients with CRP levels higher than 14.33 mg/dl on POD4, even without clinical symptoms, are considered to have an increased risk of infections, and they should be carefully observed until infectious complications are completely ruled out." (PMID 32785845, 2021). "Our study also revealed that patients with newly diagnosed DM had more severe infection symptoms such as fever, dyspnea, and cough, as well as elevated levels of inflammatory markers such as CRP, LDH, and ferritin than non-diabetic patients." (PMID 34449740, 2021). "CRP, ER, MCP-1 and PTX3 are commonly used indicators of patient infection." (PMID 34447637, 2021). "All the subjects originated from the Sundanese ethnic group, with normal liver function and no signs of infection or inflammation, and were characterized by normal CRP and IL-6 serum levels." (PMID 33954177, 2021).